CXCL9 (C-X-C motif chemokine ligand 9)
Diseases named in the same sentence as CXCL9 in open-access papers (continued):
Sharing a sentence is not in itself a finding about the gene and the disease.
tumor (continued). "In breast carcinomas, binding of extracellular Gal-9 to Tim-3 at the surface of DCs suppresses their production of CXCL9, resulting in a significantly decreased anti-tumour response, especially in the context of a treatment by paclitaxel." (PMID 36817445, 2023). "Analyzing the predictors, TMB and CXCL9 appear to have the greatest accuracy in predicting the response to immunotherapy in a heterogeneous population composed of patients with neoplasms of different origins." (PMID 36900006, 2023). "The induction of chemokines such as CXCL-9 or CXCL-10 by IFN-λ recruits CD4+ T cells into the tumor environment, and antitumor responses of CD8+ T cells and natural killer (NK) cells are enhanced in various types of tumors." (PMID 37374093, 2023). "Among markers of immune infiltration into the tumor microenvironment, CXCL9 expression also appears to be a predictor of response to ICIs (OR = 1.67 [1.38–2.03], p = 1.33)." (PMID 36900006, 2023). "PepO-primed M2 macrophages decreased the expression of tumor-supportive molecules like Arg-1, Tgfb, Vegfa and IL-10, and increased the expression of iNOS, Cxcl9, Cxcl10, TNF-α and IL-6 to inhibit TNBC growth." (PMID 37925462, 2023). "To probe the masked mechanism of CXCL9 in UCEC, we investigated the relationship between CXCL9 and tumor immune microenvironment based on the TCGA dataset." (PMID 36845675, 2023). "NPTyr-CXCL9 increased the tumor-infiltrating CD3+ T cells to 10.4% of CD45+ lymphocytes by CXCL9-mediated T-cell recruitment, while NPTyr-αPD-L1 increased the tumor-infiltrating CD3+ T cells to 8.9% of CD45+ lymphocytes by αPD-L1-enhanced T-cell activation." (PMID 37031188, 2023). "Combining nanoparticles and tumor-specific promoters enables us to drive gene expression, such as the coexpression of CXCL9 and αPD-L1, in tumor cells for enhanced cancer immunotherapy." (PMID 37031188, 2023). "Compared with our findings in Il11−/− mice and focus on IL11 regulation in tumor cell CXCL9 and MHC-I to increase CD8+ T infiltration, Huynh hinted a novel regulation besides IL11Ra for IL11 to exert immune suppression." (PMID 37365574, 2023). "In ovarian cancer, high levels of CXCL1 expression have been found to promote cancer progression by inducing cell proliferation, whereas CXCL9 has been shown to potentiate anti-tumor activity and drive a positive response to anti-PD-L1 therapy." (PMID 36969851, 2023). "Direct injection of BATF3 DCs into the tumor region restored CXCL9 and CXCL10 expression and T-cell infiltration in WNT signaling pathway-positive tumors." (PMID 37546397, 2023). "Tumors were significantly suppressed while MHC-I and CXCL9 expression for CD8+ T infiltration were remarkably increased in the tumor tissues of Apcmin/+/Il11−/− mice or Il11−/− mice induced by AOM/DSS." (PMID 37365574, 2023). "The activated Ifng/Cxcl9 axis generated by SRC-3 KO Tregs also should stimulate the expansion of a proinflammatory Th-1-cell population within the tumor microenvironment to facilitate tumor eradication." (PMID 37253006, 2023). "Here, we devise tumor-specific gene nanomedicines to mobilize tumor cells to secrete CXCL9 (T-cell chemokine) and anti-PD-L1 scFv (αPD-L1, PD-L1 blocking agent) for enhanced immunotherapy." (PMID 37031188, 2023). "Anti-PD-1 ICB treatment in combination with control AAV6 (EGFP) modestly increased CD8 T lymphocyte recruitment in GL261 by 1.4-fold and in KR158 by 2.7-fold, indicating that CXCL9 markedly improves tumor infiltration by these cells." (PMID 38014191, 2023). "From the immune response regulation aspect, 20 upregulated genes encoding chemokines with log2FC > 1.5 were selected, among which Ccl3, Ccl4, Cxcl9 and Cxcl16 shared with both tumor suppressive roles and effects in promotion of T cell infiltration 33–36." (PMID 37996458, 2023).
tumor (continued). "Similar to observations made from B16F10 and MAP tumors, expression of the GNAS R201C mutant in 4T1-HA repressed Cxcl9/10/11 expression and promoted tumor growth in comparison to expression of wild-type GNAS." (PMID 37714844, 2023). "Tumor-specific CD4+ T cells have been shown to promote CXCL9/10 expression through IFN-γ–dependent mechanisms that increase CD8+ T cell recruitment, particularly of low-affinity T cell receptor (TCR) CD8+ T cell clones." (PMID 38063199, 2023). "This nanodrug triggered immune responses against GBM through increased CXCL9 expression in the tumor environment." (PMID 38104126, 2023). "CXCL9 from cluster 2 shows high variance in the tumor-affected region and is involved in T-cell trafficking." (PMID 37285319, 2023). "This strategy would bypass host lymphocyte sequestration altogether by direct intravenous delivery of antigen-specific T cells, where tumor-tropic CXCL9 expression would facilitate directed trafficking." (PMID 38014191, 2023). "In iCCA, increased expression of the endogenous CXCL9 closely correlates with prolonged survival by regulating tumor-infiltrating NK cells and augmenting anti-tumor immune surveillance." (PMID 37138880, 2023). "The results showed that the expression of CXCL9 in tumour tissues of the NE + anti-PD-1 mAb + Vehicle group was significantly lower than that in the CTRL + Vehicle and anti-PD-1 mAb + Vehicle groups." (PMID 36646807, 2023). "The abundance of CXCL13-expressing (CD39+) CD8+ T cells and the expression of CXCL9 in the tumor microenvironment are robust predictors for ICB response in many different primary cancer types, including lung and triple-negative BC22–24,52." (PMID 37217652, 2023). "As expected, there was a higher macrophage presence for HPVOPC tumors compared to benign tissue, and this also validated that CXCR3 and CXCL9 were highly expressed in tumor cells themselves, as well as macrophages." (PMID 37686653, 2023). "CXCR3/CXCL9/CXCL10/CXCL11 axis leads to recruitment of tumor-promoting immune cells, including TAMs, T cells, etc., thus favoring tumor growth and metastasis." (PMID 37818357, 2023). "NPSur-C9AP is demonstrated to specifically co-express CXCL9 and αPD-L1 in different tumor cells, which proves the expandability of tumor-specific gene nanomedicine to increase T-cell infiltration and activation for enhanced immunotherapy." (PMID 37031188, 2023). "After nsPEF treatment, the level of CXCL9 in the tumor was significantly upregulated, and the secretion of CXCL9 by antigen-presenting cells, such as macrophages and DCs, was increased." (PMID 37046739, 2023). "Firstly, the protein expression of CXCL9 in tumor tissue was upregulated, compared with control tissue by IHC assay." (PMID 36845675, 2023). "The relationship between CK17 tumor expression and CXCL9/SPP1 expressing macrophages should be explored further." (PMID 37835599, 2023). "When combined with the anti-CXCL9 antibody, the efficacy of nsPEF in suppressing residual tumor growth was reduced." (PMID 37046739, 2023). "To further verify the effect of NE on the expression of CXCL9 in tumour tissues, we stimulated LUAD cell lines (A549 and H3122) with NE and detected the changes in CXCL9 mRNA levels by RT-qPCR." (PMID 36646807, 2023). "In concordance, high CXCL-9 levels correlated with an increase in the infiltrating anti-tumor immune cells and also with a better response to chemotherapy in BCa patients." (PMID 37958417, 2023). "On the one hand, CXCL9, 10, and 11 promoted immune response by paracrine signal, while tumor-derived autocrine signal will induce tumor cell proliferation and metastasis." (PMID 37064084, 2023). "CXCL9 was upregulated in 427 TCGA-OV tumor samples compared to 88 GTEx normal ovary samples(P < 0.001)." (PMID 37644593, 2023). "Significantly, NPTyr-C9AP group exhibited the highest tumor growth inhibition rate (78.2%) and the lowest final tumor weights due to tumor-specific coexpression of CXCL9 and αPD-L1." (PMID 37031188, 2023).
tumor (continued). "HPVOPC tumors showed higher expression when compared to benign oropharynx tissue for both CXCR3 and CXCL9, and they demonstrated higher expression in the tumor itself than in the surrounding stromal cells." (PMID 37686653, 2023). "Increasing evidence has shown that overexpression of CXCL9 mediates the recruitment of tumor-targeted CXCR3 + T cells and natural killer (NK) cells in various solid cancers, and thereby suppresses tumor growth." (PMID 37644593, 2023). "It suggested that UCEC patients with high CXCL9 abundance in tumor interstitial tissue featured a significantly better cumulative survival within the validation cohort (P=0.0023)." (PMID 36845675, 2023). "IE1 tumors also had increased scores for chemotactic interactions, mainly mediated by CCL3, CCL4, CCL5, and CXCL9, suggesting a more dynamic immune environment with increased potential for recruitment of cells from outside the tumor." (PMID 36609566, 2023). "The expression levels of CXCL9 (P = 0.0201), CXCL11 (P = 0.0385), and CXCL13 (P = 0.0288) were significantly associated with tumor stage." (PMID 36798787, 2023). "EGFR mutated tumor cells secrete cytokines to recruit various immunosuppressive cells, while activated immune cells (CD8+TRM and CXCL9+TAM) are seriously insufficient." (PMID 37671151, 2023). "Overexpressed CXCL9 has also been reported to impede tumor progression and metastasis by inhibiting angiogenesis." (PMID 36845675, 2023). "Th17 cells promote tumor immunity via the induction of CXCL9 and CXCL10, key chemokines that promote the infiltration and activation of cytotoxic NK cells and CD8+ T cells within the TIM." (PMID 37766141, 2023). "Further studies are required to determine the anti-tumor mechanisms of CXCL9- and CXCL11-expressing tumor tissues in nude mice." (PMID 37218983, 2023). "Several groups have tried to inject recombinant proteins or viral expression vectors intratumorally to build gradients of CXCL9, 10 or 11 between tumor and peripheral tissues." (PMID 37031188, 2023). "On the other hand, it has also been demonstrated that tumor-cell-derived CXCL9/CXCL10 regulates the recruitment of T cells in various tumors." (PMID 37109526, 2023). "CTLA-4 blockade also increases IFNγ and Cxcl9 expression in immunogenic tumor cells, which are crucial in type 1 immunity and vessel normalization as well as T cell recruitment." (PMID 37587450, 2023). "In melanoma, the chemokines CCL2, 3, 4, and 5 as well as CXCL9 and 10 were reported to induce effective T cell migration into the tumor microenvironment." (PMID 37443821, 2023). "Here the authors describe the design of a tumor-specific expression strategy to drive secretion of CXCL9 and an anti-PD-L1 scFv (αPD-L1) in the tumor microenvironment, promoting T cell recruitment and anti-tumor immune response in preclinical cancer models." (PMID 37031188, 2023). "The Ifn-γ and Cxcl9 secretion in tumours were increased in the anti-PD1/chidamide and were somewhat reduced in the anti-Ifn-γ detected by ELISA." (PMID 36592514, 2023). "Combining anti-PD-L1 antibody with NPTyr-CXCL9 that expressed CXCL9 significantly increased the tumor infiltration of CD3+ T cells (17.2% of CD45+ lymphocytes in NPTyr-CXCL9 & anti-PD-L1 group)." (PMID 37031188, 2023). "Tumor-resident cDC1s are crucial for regulating the trafficking of effector T cells to the TME through the secretion of CXCL9 and CXCL10, suggesting that cDC1-T-cell crosstalk is also evident at tumor sites." (PMID 36949244, 2023). "Targeting this axis directly with monotherapies to block the CXCL9/CXCL10/CXCL11–CXCR3 axis or to regulate CXCR3-A expression on the tumor cell membrane surface holds promise." (PMID 38104126, 2023). "Herein, we developed tumor-specific gene nanomedicines that utilize tumor-specific promoters to drive tumor cells to coexpress CXCL9 and αPD-L1 in situ, which effectively recruited T cells into tumors and enhanced the activation of tumor-infiltrating T cells." (PMID 37031188, 2023).
tumor (continued). "Our results were consistent with the notion that the anti-tumor immune response elicited by ICB requires the involvement of macrophage-derived CXCL9 and CXCL10." (PMID 36900218, 2023). "We found that direct intratumor delivery of AAV6 was sufficient to establish tumor-selective production of CXCL9." (PMID 38014191, 2023). "The increase in circulating IP-10 and MIG is consistent with the observed increase in RNA expression of their encoding genes CXCL10 and CXCL9 in tumor samples." (PMID 37507657, 2023). "The top differentially expressed gene in the allograft pathway, CXCL9, is of particular interest, as the expression of the chemokine CXCL9 boosts T-cell tumor infiltration and inhibits tumor growth, angiogenesis, and metastasis." (PMID 37048724, 2023). "This, in concert with anti-PD-1 ICB, significantly increases tumor infiltration by lymphocytes likely through CXCL9 engagement with its cognate receptor expressed by these cells-CXC motif chemokine receptor 3 (CXCR3)." (PMID 38014191, 2023). "On the other hand, CXCL8 is a target for solid tumor immunotherapy, and CXCL9/10 has been demonstrated to enhance the accumulation of effector T cells at the tumor site and suppress tumor growth." (PMID 36969851, 2023). "In this study, we verified that overexpressed CXCL9 as an independent prognostic biomarker in UCEC patients augmented anti-tumor immunity and was related to significantly prolonging survival." (PMID 36845675, 2023). "We found that the relative concentration of CXCL9 in tumor tissues was significantly increased after nsPEF treatment (p < 0.05)." (PMID 37046739, 2023). "CXCL9, also known as monokine induced by gamma interferon (MIG), is known to have important roles in anti-tumor immunity, especially in the recruitment of T cells." (PMID 37046033, 2023). "In our study, CXCL9 exhibited higher expression in EGFR–TKI-sensitive samples, consistent with its role in inhibiting tumor-associated angiogenesis and contributing to EGFR–TKI resistance." (PMID 37816585, 2023). "Genetic analysis reveals that MC1R signals through the GNAS-PKA axis to repress the transcription of chemokine genes CXCL9/10/11, resulting in impaired T cell infiltration into the tumor microenvironment." (PMID 37714844, 2023). "Accumulation of NK cells within the tumors contributed to slowed tumor growth and augmented T cell infiltration through induction of CXCL9 and CXCL10 via NK cell-derived IFN-γ." (PMID 38022679, 2023). "Unexpectedly, Cxcl9/Cxcl10 was largely confined to the apical surface in tumor cells from untreated KPC mice." (PMID 36472588, 2023). "The effect of K17 on immune regulation was at least partially dependent upon regulation of the CXCL9/CXCR3 axis in the tumor microenvironment." (PMID 38140561, 2023). "Tumor-infiltrating cDC1 promotes T cell infiltration by secreting CXCL9 and CXCL10 (ligands of CXCR3) to guide T cell homing." (PMID 38008741, 2023). "Studies have shown that CXCL9/10/11 are the main CFs for CD8+ T cells, and that CXCL9/10 can attract Th1 cells to the tumour microenvironment and play an important role against cancer." (PMID 37880315, 2023). "Chemokines such as C-X-C Motif Chemokine Ligand 9 (CXCL9) and CXCL10 stimulate T cell trafficking and infiltration into the tumor, where T-cell-mediated cytotoxicity liberates more tumor-associated antigens to further propagate the cancer-immunity cycle." (PMID 36700235, 2022). "Overexpression of CXCL9 in KPOVA cells enhanced recruitment of tumor-specific CD8+ T cells and reduced tumor growth." (PMID 35389889, 2022). "The mechanisms of anti‐tumour activity include induction of tumour derived cytokines (CXCL9 and 10) which attract Th‐1 cells, and subsequently, CD8+ lymphocytes and NK cells." (PMID 35445563, 2022). "Other studies showed that the chemokines CCL2, 3, 4, and 5 as well as CXCL9 and 10 were involved in T-cell migration into a melanoma tumor microenvironment." (PMID 35795658, 2022).
tumor (continued). "Studies have shown that tumor-resident cDC1s are the main source of CXCL9 and CXCL1029, and CXCL10 is a candidate for cancer immunotherapy." (PMID 35710862, 2022). "This leads to production and release of type 1 IFNs that act in an autocrine feedback loop to stimulate tumor cell production of chemokines such as CXCL9/10 and expression of other pro-inflammatory genes." (PMID 36227698, 2022). "Tumour-derived chemokines such as CXCL9, CXCL10, and CXCL11 are attracted by CXCR3 (expressed on activated CD8+ T cells), leading to their recruitment and development of anti-tumour immune response." (PMID 35406451, 2022). "The recruitment of T cells and natural killer (NK) cells into the tumor can be achieved by chemokines CXCL9, 10, 11, 16 as well as CX3CL1." (PMID 35795658, 2022). "So NLRC3 high expression represents a novel predictor for positive survival outcomes in HCC patients, and NLRC3 is involved in CD8+ T cell infiltration, which is correlated with increased CCL5 and CXCL9 in TME (tumor microenvironment)." (PMID 35145917, 2022). "ELISA analysis of tumour lysates validated the increasedexpression of T-cell chemoattractants (CXCL9 and CXCL10) uponKRASG12C inhibition." (PMID 35930804, 2022). "On the other hand, it allows us to directly attribute observed effects to CXCL9 overexpression within the tumour microenvironment." (PMID 35314795, 2022). "Attesting to the functional relevance of CXCL9, measurement of tumor growth by luminescence revealed that mice treated with anti-CXCL9 antibody had increased tumor growth as compared with those treated with irrelevant antibody." (PMID 35503658, 2022). "In the TME, M1-like macrophages are capable of recruiting and activating CD8+ T cells and NK cells via antigen presentation to the T-cell receptor and the secretion of tumor-derived chemokines including CXCL9, CXCL10, and CXCL11." (PMID 36561315, 2022). "Recent studies have revealed that ARID1A loss impairs IFN signaling, especially Th1-type chemokine (CXCL9 and CXCL10) expression, to compromise effector T-cell tumor trafficking and antitumor immunity." (PMID 36435834, 2022). "IFN-γ also enhances T cell infiltration at the tumour site through the induction of chemokines (CXCL9, CXCL10 and CXCL11)." (PMID 36230780, 2022). "Unexpectedly, despite an improved ICB treatment, we did not observe an increase in the CD3+ or CD8+ immune infiltration upon Cxcl9 overexpression in the tumours treated with the anti-PD-L1 antibody, which we once again reproduced in the IgG2b-treated tumours." (PMID 35314795, 2022). "Our findings demonstrate that the obese environment also leads to altered chemokine secretion in the tumor leading to a reduction of CXCL9 and CXCL10 in obese tumors." (PMID 35103755, 2022). "Macrophages and dendritic cells that cluster on the tumor secrete CXCL9, which significantly promoted tumor invasion through circulating T cells." (PMID 35145917, 2022). "In vivo, overexpression of Cxcl9 was preserved in about the same range as observed in vitro, as detected in the ascites of tumour-bearing mice at the end of the experiment (median 3.1 vs. 0.5 pg/mg total protein; P = 0.032)." (PMID 35314795, 2022). "Specifically, we measured IFN-γ, GranzymeB, and CXCL9, markers known to be regulated by STAT1 and are associated with T cell anti-tumour activity, effector responses and chemotaxis of anti-tumour effector T cells." (PMID 35595823, 2022). "The activation of the NF-κB signaling pathway in macrophages increases CXCL9 expression and promotes an anti-tumor TAM phenotype (M1), thereby increasing cytotoxic T cell infiltration and limiting EOC progression." (PMID 35269786, 2022). "Previous studies demonstrated that tumor cell-derived CXCL9/CXCL10 modulated T-cell recruitment in various tumors." (PMID 36284313, 2022). "For one thing, in the PRDX1/5-low group, a high level of ROS can induce the production of chemokines (for example, CXCL9), thereby recruiting T cells into the tumor." (PMID 35350568, 2022).